LINC02568 (long independently transcribed non-coding RNA 2568)
Gene: Long non-coding RNA gene on chromosome 15 (63,381,711 to 63,438,320, forward strand). Ensembl gene ENSG00000259459.
Diseases named in the same sentence as LINC02568 in open-access papers:
LINC02568 is named in the same sentence as 4 diseases in open-access papers, as found by Europe PMC text mining. Sharing a sentence is not in itself a finding about the gene and the disease. The quoted sentences say what the papers report.
breast carcinoma (2 papers, 2021 to 2023). "Furthermore, high LINC02568 levels were associated with worse prognosis in patients with breast cancer." (PMID 37303942, 2021). "We also measured LINC02568 expression in breast cancer tissues from our cohort; compared with matched para-cancer tissues, LINC02568 was overexpressed in breast cancer tissues." (PMID 37303942, 2021). "Furthermore, LINC02568 is highly expressed in ER+ breast cancer cell lines compared with normal mammary epithelial cell lines and other subtypes of breast cancer cell lines, such as triple‐negative breast cancer." (PMID 37404090, 2023). "To examine whether LINC02568 regulation of the malignant behaviors of ER+ breast cancer cells is through miR‐1233‐5p, we first examined the effects of miR‐1233‐5p itself." (PMID 37404090, 2023). "Next, to examine whether CA12 contributes to LINC02568 function in cellular pH control and malignant phenotypes of ER+ breast cancer cell, we performed rescue experiments in which CA12 was introduced when LINC02568 was knocked down in MCF7 cells." (PMID 37404090, 2023). "Furthermore, LINC02568 is highly expressed in ER+ breast cancer cell lines compared with normal mammary epithelial cells and other subtypes of breast cancer cells, such as triple‐negative breast cancer." (PMID 37404090, 2023). "Significant LINC02568 overexpression was identified in breast cancer tissues." (PMID 37303942, 2021). "Therefore, LINC02568 plays a pro-oncogenic role in breast cancer progression by targeting the miR-874-3p/CCNE1 axis." (PMID 37303942, 2021). "Therefore, LINC02568 silencing impaired breast cancer cell growth in vivo." (PMID 37303942, 2021). "Thus, LINC02568 functioned as a tumor promoter during breast cancer progression." (PMID 37303942, 2021). "Taken together, our data revealed that LINC02568 regulates nearby CA12 gene in cis, and the expression of both genes is highly correlated in ER+ breast cancer." (PMID 37404090, 2023). "The requirement of LINC02568 for MCF7 cell proliferation, colony formation, migration, and invasion were confirmed through siRNA specifically targeting LINC02568, which was further demonstrated in another ER+ breast cancer cell line, T47D." (PMID 37404090, 2023). "LINC02568 therefore serves as a potential therapeutic target in ER+ breast cancer, and ASO targeting LINC02568 might provide a promising treatment option for ER+ breast cancer patients with primary and acquired endocrine therapy drug resistance." (PMID 37404090, 2023).
breast tumor (1 paper, 2023). "In breast tumor cells, the high expression of LINC02568 maintains the high transcriptional activity of CA12, and therefore pH homeostasis." (PMID 37404090, 2023).
tumor (2 papers, 2021 to 2023). "As expected, LINC02568 knockdown significantly diminished the effects of estrogen‐induced tumor growth." (PMID 37404090, 2023). "Meanwhile, LINC02568 contributes to tumor‐specific pH homeostasis by regulating carbonic anhydrase CA12 in cis in the nucleus." (PMID 37404090, 2023). "The expression of LINC02568‐target genes was also found to be inhibited in a synergistic manner in tumor tissues with combination treatment." (PMID 37404090, 2023).
LINC02568 also shares sentences with these, for which no sentence is quoted: cancer (1 paper).